NAMPT (nicotinamide phosphoribosyltransferase)
Diseases named in the same sentence as NAMPT in open-access papers (continued):
Sharing a sentence is not in itself a finding about the gene and the disease.
Obesity (continued). "Nicotinamide phosphoribosyltransferase (NAMPT)-mediated nicotinamide adenine dinucleotide (NAD+) biosynthesis in major metabolic organs such as the liver, adipose tissue, and skeletal muscle plays a crucial role in obesity- and aging-associated organ derangements." (PMID 36986224, 2023). "NAMPT/visfatin is involved in energy metabolism and is also known to have pro-inflammatory properties and, thus, may be helpful as a potential biomarker for obesity, insulin resistance, and type 2 diabetes (T2D) status." (PMID 36831180, 2023). "In addition, the feasibility of intravenous administration of 300 mg NMN suggests that NAMPT may be activated and TG levels may be suppressed, which may help improve obesity and prevent aging." (PMID 36225528, 2022). "Specifically, interactions between miR-130b-3p/ATXN2, and miR-142-5p/NAMPT may play important roles in regulation of host metabolism, given that loss of function mutations in both ATXN2 and NAMPT are associated with obesity and diabetes mellitus." (PMID 30020932, 2018). "We have previously shown that the elevated enzymatically active NAMPT levels in obese children are mainly derived from leucocytes and inducible by lipopolysaccharide and hence that NAMPT may serve as a biomarker or even mediator linking obesity, inflammation and insulin resistance." (PMID 28837586, 2017). "Nicotinamide phosphoribosyltransferase (NAMPT) is a pleiotropic protein implicated in the pathogenesis of acute respiratory distress syndrome, aging, cancer, coronary heart diseases, diabetes, nonalcoholic fatty liver disease, obesity, rheumatoid arthritis, and sepsis." (PMID 28333140, 2017). "Moreover, NAMPT was shown to be differentially regulated in pathophysiological conditions like cancer, inflammatory disorders, heart diseases and metabolic disorders, such as type 2 diabetes, obesity and non-alcoholic fatty liver (NAFLD)." (PMID 28974242, 2017). "DEGs of NAMPT, TLR9, PTGS2, HBD, and PCSK1N might be associated with obesity." (PMID 29132311, 2017). "And up-regulated genes-NAMPT, TLR9, PTGS2, HBD, and PCSK1N might be associated with obesity risk." (PMID 29132311, 2017). "Furthermore, a rare SNP in visfatin (NAMPT/PBEF1), a gene known to be involved in the negative arm of the clock (not shown in Figures), has been associated with protection from obesity in human populations." (PMID 28977444, 2017). "Moreover, in the present study, we provide original evidence that also systemic factors, such as NAMPT, whose levels are increased in obesity, metabolic syndrome, and diabetes mellitus, may interfere with periodontal healing." (PMID 24288440, 2013). "Therefore, increased NAMPT levels, as found in obesity, may represent at least one mechanism, whereby obesity could confer an increased risk of periodontitis in obese individuals." (PMID 24058270, 2013). "Next, we sought to explore the reasons behind the paradoxical changes of NAMPT and NAD+/NADH ratio levels in obesity." (PMID 39901373, 2025). "Our findings establish the role of NAMPT acetylation level in UAM injury and shed light on potential mechanisms driving obesity‐related declines in UAM function." (PMID 39901373, 2025). "Intervention targeting NAMPT has the potential to break the vicious cycle of SIRT1/NAMPT/NAD+/SIRT1 and reverse the clinical course of obesity induced OSA." (PMID 39901373, 2025). "A novel link between obesity and cisplatin resistance in osteosarcoma is established, highlighting the A1BG/NAMPT/PARP1 axis as a critical driver." (PMID 40560034, 2025). "In animal studies, there is strong experimental evidence that NAMPT (nicotinamide phosphoribosyltransferase), the key and rate-limiting enzyme in NAD+ biosynthesis, is down-regulated in obesity." (PMID 37761000, 2023). "Herein, we aimed to review in detail the regulatory mechanisms and importance of intestinal NAMPT-mediated NAD+ biosynthesis in regulating intestinal homeostasis and GLP-1 secretion in obesity and aging." (PMID 36986224, 2023).
Obesity (continued). "Consistent with the findings that intestinal AMPK, which mediates NAMPT activation, is impaired in glucose intolerance, HFD-induced obesity, and aging downregulates the major NAD+-generating enzymes, including NAMPT, and reduces intestinal NAD+ levels." (PMID 36986224, 2023). "The novel adipokine visfatin, also known as nicotinamide phosphoribosyl transferase (NAMPT), shows increased levels in obesity, gynecological diseases, and breast cancer patients." (PMID 36830834, 2023). "The expression of NAMPT, the rate-limiting enzyme in the salvage NAD+ biosynthetic pathway, decreases with aging and obesity in various organs, including in white and brown adipose tissue, liver, skeletal muscle, hippocampus, and retina." (PMID 36986224, 2023). "Knockout of NMNT gene, knockdown of NMNT expression with siRNA, and chemical inhibition of NMNT activity promote the NAD+ salvage pathway via the enzyme NAMPT and by increasing NMN to resist HFD-induced obesity." (PMID 35563288, 2022). "DS68702229 (compound 44) was identified as a potent NAMPT activator (EC50 = 0.046 μM) that increases cellular NAD+ levels and is a promising anti-obesity drug candidate." (PMID 35903330, 2022). "Visfatin is an adipocytokine also known as nicotinamide phosphoribosyltransferase (NAMPT), which has a potential role in the pathophysiology of metabolic disorders such as hypertension and obesity." (PMID 30618791, 2018). "It has been well demonstrated that the protein expression of NAMPT is decreased, while the level of PARP1 is increased during HFD feeding and obesity, which leads to NAD+ depletion." (PMID 28786950, 2017). "Visfatin also known as pre-B cell colony enhancing factor (PBEF) or nicotinamide phosphoribosyltransferase (NAMPT) is a 52-kDa protein with apparently insulin-mimetic actions and increased plasma concentrations in patients with obesity and T2D." (PMID 24829560, 2014). "NAMPT and vaspin play roles in the intricate molecular processes related to T2DM and obesity." (PMID 39051061, 2024). "Additionally, research has shown that IRW can upregulate the expression of nicotinamide phosphoribosyltransferase (NAMPT) protein in mouse muscle cells, improving metabolic levels and alleviating obesity." (PMID 34602857, 2021). "The extracellular form of NAMPT, PBEF, or Visfatin is known as extracellular NAMPT (eNAMPT, as opposed to intracellular NAMPT, iNAMPT), an adipocytokine that is expressed in visceral fat tissue and whose circulating levels correlate with obesity." (PMID 31119097, 2019). "The IL6, LEPR, NAMPT, and AMD1 gene variants previously found to associate among Indian children did not associate with risk of obesity or obesity-related quantitative measures among Caucasian children and juvenile men from Denmark." (PMID 26558825, 2015). "The current study illustrates that four variants (IL6 rs2069845, LEPR rs1137100, NAMPT rs3801266, and AMD1 rs2796749) implicated in childhood obesity among Indians are not strongly associated with obesity among Danish children and juveniles." (PMID 26558825, 2015). "Recently, increased levels of NAMPT have also been found in patients with periodontitis, irrespective of the presence of obesity." (PMID 24288440, 2013). "FTO and NAMPT/PBEF/visfatin are thought to play a role in obesity but their transcriptional regulation in adipocytes is not fully understood." (PMID 21687707, 2011). "However, in obesity, we found that increased NAMPT levels are not followed by increased NAD+ levels." (PMID 39901373, 2025). "Therefore, we hypothesized that, in obesity, the balance between NAD+/NADH ratio and the levels of NAMPT is regulated by the enzyme NAMPT through acetylation." (PMID 39901373, 2025). "This study reveals a novel mechanism by which obesity, through the abundant peritumoral adipocytes characteristic of tumors in obese individuals, promotes cisplatin resistance in osteosarcoma, highlighting the A1BG/NAMPT/PARP1 axis as a promising therapeutic target." (PMID 40560034, 2025).
Obesity (continued). "While diabetes alone did not seem to impact tumor NAMPT expression, patients with obesity and/or diabetes had a significantly higher likelihood of having NAMPT- PDAs in comparison to patients without obesity and diabetes (31/71 (43.7%) vs. 24/86 (27.9%), P = 0.04)." (PMID 30856230, 2019). "Therefore, we speculated that the reduction of hepatic NAMPT expression in both HFD-fed C57BL/6J and ApoE KO mice might be a compensatory down-regulation to counteract the metabolic stress imposed by obesity or abnormal cholesterol metabolism." (PMID 27229177, 2016). "However, the role of NAMPT in obesity‐induced muscle impairment has not been fully clarified." (PMID 39901373, 2025). "However, a previous study has reported that NAMPT is related to only T2D and not obesity." (PMID 30755828, 2019). "Interestingly, NAMPT is also present at high levels in gingival crevicular fluid (GCF), gingival tissues, and serum from patients afflicted with periodontitis, irrespective of the presence of obesity." (PMID 24288440, 2013).
breast carcinoma (57 papers, 2012 to 2026). "This parallels previous studies on other cancers, such as colorectal and breast cancers, in which NAMPT has been implicated in promoting tumor progression through NAD+‐dependent pathways." (PMID 39988985, 2025). "Several studies have demonstrated that NAMPT inhibition causes mitochondrial dysfunction in cancer cells in breast carcinoma, leukemia, pancreatic cancer and Burkitt’s lymphoma." (PMID 37175631, 2023). "For instance, extracellular NAMPT (eNAMPT) released from melanoma cells and the overexpression of NAMPT in breast cancer cells have both been linked to the activation of AKT." (PMID 36160449, 2022). "According to the obtained results, NAMPT was recognized as a target for binding of miR-154 and the levels of this miRNA was inversely associated with both mRNA and protein levels of NAMPT in breast cancer cell lines." (PMID 31675930, 2019). "For example, NAMPT overexpression in breast cancer cells and extracellular NAMPT (eNAMPT) released by melanoma cell have both been associated with AKT phosphorylation." (PMID 32010616, 2019). "Some studies have indicated that inhibition of NAMPT expression is associated with a remarkable increase in metabolic collapse and apoptosis in breast cancer cell lines both in vivo and in vitro." (PMID 31675930, 2019). "Recent clinical studies have shown that elevated NAMPT expression is associated with poor survival in endometrial and breast cancers." (PMID 25946974, 2015). "In breast cancer patients, the levels of serum NAMPT were higher compared with healthy individuals, suggesting that serum NAMPT may be a diagnostic parameter for breast cancer." (PMID 36443772, 2022). "Over-expression of NAMPT in breast cancer tissue is associated with poor survival." (PMID 31231467, 2019). "Protein expression analysis via the HPA database, corroborated by immunohistochemical staining, confirmed these findings, highlighting the elevated presence of NAMPT in breast cancer tissues." (PMID 40083697, 2025). "Our analysis utilizing the GEPIA2021 database revealed a significant upregulation of NAMPT expression in breast cancer tissues, particularly within the M2 macrophage subset, as compared to M1/M0 macrophages and monocytes." (PMID 40083697, 2025). "NAMPT expression was substantially elevated in TNBC tissues relative to normal or other breast cancer subtypes (P = 0.003)." (PMID 40083697, 2025). "Transcription factors POU2F2, miR-548b-3p, and miR-206 regulate NAMPT expression in breast cancer cells." (PMID 37491379, 2023). "The expression of NAMPT is increased in urothelial carcinoma, breast cancer, stomach cancer, esophageal cancer, colorectal cancer (CRC), ovarian cancer, prostate cancer, glioblastoma, and melanoma." (PMID 38116009, 2023). "NAMPT, one of the rate-limiting enzymes of NAD+ biosynthesis, has been shown to be overexpressed in breast cancer and associated with breast cancer proliferation and invasiveness." (PMID 37006438, 2023). "By studying the differences in NAD+ regulation in these two breast cancer cell lines, we demonstrate that NAMPT is expressed at higher levels in 231 cells than in MCF7 cells." (PMID 37583931, 2023). "In contrast, NAMPT expression silencing led to a significant induction in metastatic capability as compared with the controls in breast cancer." (PMID 35565188, 2022). "In one study, NAMPT appeared to promote breast cancer cell proliferation via the upregulation of Notch1, which resulted in the activation of the NF-κB signaling axis." (PMID 35565188, 2022).
breast carcinoma (continued). "Contrarily, the tumor suppressor and transcription factor Foxo1 binds to the NAMPT gene’s 5' flanking region and reduces the expression of NAMPT in breast cancer cells, an action that is counteracted by the insulin-PI3K-AKT signaling pathway." (PMID 36160449, 2022). "Specifically, NAMPT mRNA is the target of miR-26b in colorectal cancer, miR-23b in melanoma, miR-381, miR-206, miR-494 and miR-154 in breast cancer cells, and miR-206 in pancreatic cancer." (PMID 36160449, 2022). "In breast cancer, NAMPT upregulated the expression of the vascular endothelial growth factor (VEGF) genes, matrix metalloproteinase (MMP)-9 and MMP-2, which indicates its potential impacts on angiogenesis." (PMID 35565188, 2022). "A recent study has shown that Akt activation by insulin increases the NAMPT expression in human breast cancer MCF-7 cells." (PMID 35326191, 2022). "A breast cancer study enrolling 176 cancer biopsy tissues indicated that NAMPT is a prognostic biomarker due to the finding its correlation with shorter survival." (PMID 35565188, 2022). "Next, NAMPT mRNA expression was confirmed in breast cancer cell lines by RT-qPCR, and higher NAMPT expression levels were observed in MDA-MB-231 and BT549 cell lines." (PMID 33912035, 2021). "Specifically, NAMPT mRNA was found to be a target of miR-381, miR-206, miR-494, and miR-154 in breast cancer cells, of miR-23b in melanoma, of mir-206 in pancreatic cancer and miR-26b in colorectal cancer." (PMID 34068917, 2021). "A study including 176 breast cancer patients also demonstrated that higher NAMPT levels are correlated with poorer survival, with high-grade tumors having significantly higher NAMPT/p73 mRNA ratios." (PMID 33912035, 2021). "In our study, NAMPT expression was verified in breast cancer cell lines and mammary epithelial cell lines, and the results were in accordance with those previously obtained in a range of solid tumors, including breast cancer." (PMID 33912035, 2021). "In breast cancer cell lines, miR-381 expression is downregulated, and NAMPT protein expression is upregulated." (PMID 33324542, 2020). "NAMPT is overexpressed in various cancers, including breast cancer, colon cancer, and gastric cancer (GC)." (PMID 33324542, 2020). "In the current study, a negative correlation was found between miR-154 and NAMPT expression (under- and over-expressed, respectively) in breast cancer cells, suggesting the inhibitory effect of miR-154 on NAMPT expression." (PMID 31675930, 2019). "Manipulation of NAMPT expression is, therefore, a reasonable strategy to overcome breast cancer development and progression." (PMID 31611752, 2019). "On the contrary, up-regulation of NAMPT in breast cancer patients is closely related to poor response to chemotherapeutic drugs such as doxorubicin." (PMID 31675930, 2019). "At the mRNA level, NAMPT gene revealed a significantly reduced expression in both breast cancer cell lines (P < 0.001) due to miR-154 augmentation by its mimic." (PMID 31675930, 2019). "Studies have shown that NAMPT is highly expressed in the serum of patients with gastric cancer, pancreatic cancer, colorectal cancer, breast cancer, and other cancers." (PMID 31817697, 2019). "Inhibiting NAMPT can also make the ERneg breast cancer sensitive to additional chemotherapies as observed in vitro." (PMID 31231467, 2019). "NAMPT has been reported to be highly expressed in various tumors, such as gastric cancer, breast cancer, pancreatic cancer and prostate cancer, to promote tumor cell glycolysis, proliferation, survival, invasion, metastasis and chemotherapy resistance." (PMID 31448236, 2019). "Our study demonstrated that the non-canonical CACGCG E-box functions as a c-MYC binding site in HCC-B, and that c-MYC binds to the CACGCG motif in the NAMPT gene promoter in a breast cancer cell line." (PMID 31739577, 2019).